RNU6-1266P (RNA, U6 small nuclear 1266, pseudogene)
Gene: Small nuclear RNA gene on chromosome 10 (77,776,951 to 77,777,055, reverse strand). Ensembl gene ENSG00000199664.
Homologues: Orthologues: chimpanzee U6 (98% identical), dog U6 (92% identical), mouse Gm25810 (91% identical), pig U6 (91% identical), guinea pig U6 (90% identical), dog U6 (89% identical), dog U6 (88% identical), rabbit U6 (86% identical), guinea pig U6 (85% identical), rat LOC120097653 (83% identical), rat LOC120098444 (73% identical), guinea pig U6 (48% identical). Paralogues in human: RNU6-1060P (93% identical), RNU6-15P (93% identical), RNU6-12P (92% identical), RNU6-13P (92% identical), RNU6-31P (92% identical), RNU6-32P (92% identical), RNU6-33P (92% identical), RNU6-41P (92% identical), RNU6-1 (91% identical), RNU6-116P (91% identical), RNU6-11P (91% identical), RNU6-17P (91% identical), and 1286 more.